IL1B (interleukin 1 beta)
Diseases named in the same sentence as IL1B in open-access papers (continued):
Sharing a sentence is not in itself a finding about the gene and the disease.
tumor (continued). "Not surprisingly, as an activator of IRAK signaling, the proinflammatory cytokine IL-1β participates in tumor growth, invasion, metastasis, angiogenesis, and chemoresistance." (PMID 35211171, 2022). "IL-1β was also described to be required for in vivo invasiveness and angiogenesis in several tumor cell lines." (PMID 35681719, 2022). "Neutralization of IL-1β will enhance the anti-tumor activity of PD-1 and be accompanied by increased infiltration of CD8+ T cells." (PMID 35493517, 2022). "IL1β is a pro-inflammatory cytokine, and inhibiting this molecule has been shown to prevent the infiltration of immune cells into primary tumours, facilitating their growth." (PMID 36230739, 2022). "IL-1β was found to be able to transform the bone stroma into a niche favorable for metastasis, and promote bone colonization of metastatic tumor cells." (PMID 36237303, 2022). "Suppression of IL-1β expression has been shown to reduce tumor growth and prevent shedding of tumor cells from the primary site into circulation." (PMID 35086565, 2022). "Cxcl1 transcription in CAFs—another key iCAF marker—was similarly induced nearly 22-fold following co-culture with tumor-infiltrating neutrophils, and significantly abrogated with either IL-1β or IL-1R1 inhibition (all p<0.0001)." (PMID 36107485, 2022). "These cytokines are expressed in an altered manner; IL-1β, TNF-α, IL6, IL10, IFN-γ, and CX3CL1 are overexpressed and are correlated with the onset of pain, as it was discovered that they are linked to tumor progression and aggressiveness." (PMID 35054779, 2022). "Tumour-derived IL-1β enhances infiltrating TANs, inhibiting tumour growth, and improving patient survival." (PMID 35998812, 2022). "M2b/M1M2bM2c/M2b/M1M2bM2c is maintained in a cycle due to the action of a pro-inflammatory IL-1β.Like IL-6, IL-1β has two sides to a story: tumor promotion and tumor inhibition." (PMID 36544764, 2022). "In 1,4-dihydroxy quininib treated UM explants, a significant negative correlation was observed between IL-13 secretion and tumour thickness; IL-1β secretion and tumour dimensions (LUD and LUH); IL-8 secretion and tumour dimensions; and TNF-α secretion and LUH." (PMID 36698840, 2022). "Vascular cell adhesion molecule (VCAM)-1 mediates cell-to-cell interactions and can induce the expression of VCAM-1 in the inflammatory tumor microenvironment by high expression of IL-1β." (PMID 36225358, 2022). "Initially, in the control and in the early stages of the tumor, the IL-1β levels show a significant scatter among individuals, whereas those of TNFα and IL-10 have a narrower spread." (PMID 35053477, 2022). "Chronic inflammation is widely recognized as one of the hallmarks of carcinogenesis, tumour progression and metastasis, and IL1B exerts its oncogenic effects by promoting chronic inflammation." (PMID 35083859, 2022). "COX-2 can also trigger various cellular inhabitants favoring the tumor microenvironment, such as IL-1b, TGF-β, and VEGF." (PMID 35898583, 2022). "Immune and stromal cell populations included 2 populations: Macrophages 1 (c1: C1qa, C1qb, C3aR1, Cd68, Csf1r, Tlr2, and Cd86) and 2 (c6 + c9: Ccr7, Csf2rb, Il1b, and Cd74) expanded in PNs as a percentage of total tumor cells." (PMID 36134665, 2022). "Our previous reports demonstrated a role for caspase-1 in monocytic MDSCs as a tumor growth mediator in a T cell-independent manner to warrant IL-1β blockade in cancer therapeutics." (PMID 36439171, 2022). "Our findings demonstrate for the first time that efferocytosis of apoptotic tumor cells activates myeloid-intrinsic NLRP3/caspase-1/IL-1β signaling in the tumor microenvironment." (PMID 36439171, 2022). "IL-1β derived from tumour and stromal cells forms an IL-1β–IRAK4 feedforward signal that drives tumour fibrosis, chemoresistance and poor prognosis in PDAC." (PMID 35986089, 2022). "This myeloid NLRP3/IL-1β signaling axis promotion of tumor growth was found to be gasdermin D independent." (PMID 36439171, 2022).
tumor (continued). "For instance, Salmonella LPS can increase the expression of IL-1β and exert the anti-tumor effect through the inflammasome and the Toll-like receptor 4 (TLR4)-mediated signaling pathway." (PMID 35757741, 2022). "Mechanically, tumor-secreted cathepsin C promoted the maturation and release of IL-1β in pulmonary neutrophils by activating the neutrophils membrane localization proteinase 3 (PR3) through enzyme digestion." (PMID 35719975, 2022). "Under persistent hypoxia of the TME, the M2-like TAMs can release IL-1β induced by necrotic debris of tumor cells, which promotes the expression of PD-L1 and facilitates the recruitment and infiltration of MDSCs to the immune microenvironment of HCC." (PMID 36615387, 2022). "Compared to mosaically introduced RasG12V cells in normal skin, those in doxorubicin-treated skin relatively strongly expressed cdkn2a/b, il1b, 1l11b, and ROS and efficiently induced tumour-like cell masses." (PMID 35304872, 2022). "Another FFL stimulated by brain metastases involves increased expression of hepatocyte growth factor (HGF) receptor (c‐Met) in tumor cells that leads to high IL1β secretion." (PMID 35506376, 2022). "In fact, chemotherapy and radiation can induce the production of IL-1β by either cancer cells or tumor infiltrating cells." (PMID 36497475, 2022). "IL-1β, a pro-inflammatory cytokine abundantly expressed in the tumor microenvironment, plays a major role in cancer invasiveness, progression, and metastases." (PMID 35223517, 2022). "The removal of ICOS-Fc from IL MIX resulted in it having a lesser effect on tumor growth (mass, volume), cell proliferation (Ki67), and immune modulation, in terms of IL-1β, IL-6, and IL-10 expression." (PMID 36500861, 2022). "IL-1β, secreted from the tumor microenvironment or the tumor cells, stimulates inflammation that induces invasiveness." (PMID 35511379, 2022). "A study suggests that IL-1β produced by macrophages in the tumor microenvironment promotes tumor growth and metastasis by increasing the expression of novel targets related with angiogenesis and enhancing antiapoptotic signaling in tumor cells." (PMID 35036439, 2022). "We measured the impact of uPAR inhibitors on the quantity of migrating cells invading through a modified Boyden invasion chamber to assess the impact of EGCG and IL-1β on tumor invasion." (PMID 36430487, 2022). "Tumor cells create a positive feedback loop with macrophages, producing IL-1β and promoting Wnt/β-catenin signaling, which confers drug resistance." (PMID 35884974, 2022). "Specifically, great interest has been given to IL-1β which is increased in several cancers and has proven to promote tumorigenesis, tumor invasiveness and immunosuppression." (PMID 36712972, 2022). "The molecules link between NF‐κB‐activated inflammation and tumour promotion has been proposed, such as IL‐1β, IL‐6 and TNF‐α, which are downstream targets of NF‐κB." (PMID 36124714, 2022). "AIM2 was also required for the production of IL-1β and IL-18, which promoted Treg accumulation and tumor growth in vivo." (PMID 35739593, 2022). "Our results demonstrated that extracellular ATP induces the functional activation of NLRP3 in tumor-induced MDSCs ex vivo, accompanied by IL-1β release." (PMID 36032139, 2022). "Detailed phenotyping revealed that HFHCD drives Ly6Chi monocytosis, which directly supplied myeloid-derived cell accumulation into the growing tumor, a process controlled by IL-1β and driven by chemokine production." (PMID 36104342, 2022). "Specifically, it is thought that IL-1β is secreted into the tumor microenvironment, activating inflammation and promoting invasion." (PMID 35565306, 2022). "Blocking of IL-1β also increased the tumor infiltration by CD8+ T lymphocytes and decreased immunosuppression." (PMID 35086565, 2022). "NLRP3 plays a significant role in establishing the microenvironment surrounding the PDAC tumor by modulating the expression of IL-1β." (PMID 36389791, 2022).
tumor (continued). "Serum IL-1β levels rise in multiple investigations on cancer patients with various cancer types, showing a tumor-type independent systemic phenomenon and pointing to a relationship between disease severities in cancer patients." (PMID 36294905, 2022). "IL-1β has been shown to have a strong tumor-promoting role while conversely, IL-18 has anti-tumorigenic effects." (PMID 36439171, 2022). "Once there, the DCs phagocytose the tumor cells and release pro-inflammatory mediators in the tumor, such as IL-1β, IL-18, IFN-γ, among others." (PMID 36015189, 2022). "Much evidence depicts that intense MMP-9 and IL-1β staining were observed in M2-like macrophages and tumor cells at the invasive prostate zone." (PMID 36117852, 2022). "Mechanistically, IL-1β promotes T-cell homing to the tumor site and improves T cell survival and activation." (PMID 35517498, 2022). "IL-1β promotes chronic inflammation, fibrosis, endothelial cell activation, tumour angiogenesis and the induction of immunosuppressive cells to promote tumour progression." (PMID 35986089, 2022). "Studies have shown that certain inflammatory factors, such as IL-1β, play a role in promoting tumour invasion." (PMID 35902905, 2022). "M1 macrophages are considered anti-tumorous as they kill tumor cells by producing pro-inflammatory cytokines, such as IL-1β and IL-12." (PMID 35719915, 2022). "In line with our NF-κB findings, IHC revealed a largely decreased expression of phosphorylated STAT3 (p-STAT3) in the tumor lesions of anti–IL-1β–treated mice at the age of 14 or 18 weeks." (PMID 35471938, 2022). "IL-1β activates both RAS and Wnt-1 which mediate the elevation of HIF-1α, thus inducing a HIF-1α/IL-1β autocrine loop in GBM tumor cells." (PMID 35572545, 2022). "As described by others, we confirmed that the downstream mediator responsible for tumorigenesis was IL-1β as its depletion resulted in significant reduction of tumor growth which phenocopied both the caspase-1 and NLRP3 null mice." (PMID 36439171, 2022). "Levels of VEGF, CXCL-1 and IL-1β were also markedly lower in inflammatory AOM/DSS tumours of Gpr35ΔMΦ compared with Gpr35fl/fl mice." (PMID 33758004, 2022). "For example, a report showed that macrophages produced higher levels of TNF, IL6, and IL‐1β after stimulation with H. capsulatum, whereas a different report showed that macrophages treated with dying tumor cells exhibited M2 phenotype." (PMID 35037422, 2022). "Deletion of IL1β prevented tumor-induced expansion of JAM-A+ cells within monocytes in both LLC and Py8119 tumor-bearing mice." (PMID 36531986, 2022). "Whereas IL-1β is secreted in large quantities by the tumor sites, promoting invasiveness, stemness, and immune suppression." (PMID 35511379, 2022). "In an ex vivo study of 239 biopsies, IL-1β production was measured using tumor biopsies stimulated with PMA and correlated to disease severity." (PMID 35631400, 2022). "Inhibiting the IL-1β/ESE3 (PSCs)/IL-1β-positive feedback loop is a promising therapeutic strategy to reduce tumour fibrosis and increase chemotherapeutic efficacy in PDAC." (PMID 35986089, 2022). "IL1B promotes myeloid-derived suppressor cells (MDSC), angiogenesis, and endothelial cell activation and supports the immunosuppressive activity of tumor-associated macrophages (TAMs)." (PMID 35163468, 2022). "Firstly, GBM tumor cell-induced IL-1β drives the HIF-1α-IL-1β autocrine loop to maintain a persistently elevated IL-1β level that activates RelB/p50 complexes, thus attracting or polarizing GAMs." (PMID 35572545, 2022). "The anti-tumor phenotype of mast cells is possibly driven by the presence of IL1B+ macrophages via IL1B/ADRB2 ligand-receptor interaction." (PMID 35311066, 2022). "In this regard, Il-1β activates the Wnt signaling pathway directly by inactivating GSK3β, resulting in increased β-catenin levels and promoting Wnt signaling during tumor development." (PMID 35511336, 2022).
tumor (continued). "Multiplex cytokine assays revealed that macrophage-tumor coculture increased macrophage secretion of IL-1β, thereby inducing the expression of intercellular adhesion molecule 1 (ICAM1; also known as CD54) in HNSCC." (PMID 36264639, 2022). "The inhibition of IL-1β has proven considerable efficacy in suppressing tumor progression through inhibiting angiogenesis and osteolytic activity of PCa cells." (PMID 36237303, 2022). "This action of SIRPγhi cells to enhance expression of an immune checkpoint in the tumor as a whole is achieved through autocrine/paracrine-dependent signaling via cytokines, such as IL-1β and GM-CSF, regulated by YAP." (PMID 35229723, 2022). "Immunohistochemistry (IHC) was used to evaluate the differential expression of major PRGs (GSDMC, GSDMD, GSDME, NLRP3, NLRC4, IL1B) in selected tumor types (COAD, HNSC, KIRC, LIHC, LUAD, LUSC)." (PMID 36605187, 2022). "Specifically, several cytokines and growth factors released by immune cells and tumor cells, such as IL-1β, IL-6, and TGF-β promote the development of MDSCs." (PMID 35656301, 2022). "Efferocytosis of tumor apoptotic debris activates NLRP3-dependent inflammasome signaling and IL-1β production, which drives tumor progression in vivo." (PMID 36439171, 2022). "Inflammatory cytokines such as IL-1β, TNFα, and IFNγ are produced to combat the initial tumor via activation of NF-κB, STAT1, and NLRP3 inflammasome pathways." (PMID 36555392, 2022). "IL1B secreted by the M1 macrophages induces the expression of PD-L1, which impedes the cytotoxic T cells from directing the anti-tumor effect." (PMID 35884843, 2022). "Inflammatory cytokines, including tumor necrosis factor-alpha (TNF-α) and IL-1b, can influence the expression of transcription factors that induce epithelial to mesenchymal transitions, which enable the dissemination of tumor cells." (PMID 36140220, 2022). "As tumor-induced JAM-A upregulation was IL1β-dependent, our findings are likely relevant for other diseases associated with elevated systemic IL1β levels." (PMID 36531986, 2022). "As a result, inflammatory cytokines are released from the inflammatory cells (TNF-α, IL-1β, IL-6, IL-8, etc.), promoting tumor invasion and progression." (PMID 35054779, 2022). "To confirm the inhibition of Fn by SNH, we tested the effects of SNH on the Fn-induced inflammation in vivo, and the inflammatory cytokines TNF-α and IL-1β in the tumor xenografts and colon tissues from the HCT116-engrafted mice were analyzed by qPCR." (PMID 36551597, 2022). "Among these 9 candidate targets, AGT, DRD2, IL-1B, and IL-6 were significantly increased in primary tumor compared with the normal tissues, while ALB, IL-10, and IGF1 were significantly decreased in COAD tissues." (PMID 35280511, 2022). "Once cancer cells are disseminated in the bone, interactions between tumour cells and the bone metastatic niche (osteoblasts, haematopoietic stem cells and blood vessels) lead to increased secretion of IL1β in the local environment." (PMID 36230739, 2022). "A group of cells was shown to highly express CCL4L2, CCL4, and other chemokines and their receptors as well as IL1B, indicating the function of promoting tumor growth." (PMID 36304995, 2022). "Considering that FLS can be activated by TNF-α and IL-1β and exhibit biological behaviours similar to tumour cells, we used IL-1β and TNF-α to treat human RA-derived FLS MH7A cells to construct RA cell models." (PMID 36405992, 2022). "In gastric cancer, TG2 upregulation was shown to enhance inflammation and promote tumor growth by recruiting macrophages to the tumor milieu via Il-1β-mediated induction of CCL2 and CXCL10." (PMID 35681474, 2022). "IL-1β plays a key role in carcinogenesis and tumour growth owing to its importance in mediating the inflammatory response." (PMID 35986089, 2022). "In carcinogenesis, IL-1β is suggested to increase angiogenesis and promote tumour invasiveness and metastasis." (PMID 36678401, 2022).
tumor (continued). "Findings identify a new modality for immune evasion in PDAC that depends on IL-1β production by tumor cells through TLR4-NLRP3 inflammasome activation." (PMID 36389791, 2022). "Both in vitro and in vivo tumor xenograft assays show that the expression of CD133, known as a GSC marker, is associated with increased neutrophil recruitment and IL-1β signaling, underlining the crosstalk between GSCs and neutrophils." (PMID 35920986, 2022). "In agreement with our in vitro data, we observed lower levels for IL-1b in myeloid cells from tumor-bearing cKO mice." (PMID 35992852, 2022). "The other is that NLRP3 inflammatory bodies are activated by ATP to release tumor suppressor factor IL-1β, inducing pyroptosis, thereby removing malignant tumor precursor cells and achieving the effect of anti-tumorigenesis." (PMID 36497244, 2022). "NLRP3/Caspase-1/IL-1β signaling axis within the tumor-infiltrating mononuclear phagocytes promotes tumor growth in GSDMD independent manner in vivo." (PMID 36439171, 2022). "IL-1β stimulation of tumor cells activates multiple signaling pathways involving protein kinase B, MAPK, and NF-κB." (PMID 35805039, 2022). "IL-1β is secreted at the time of tumor initiation, and the level then decreases, but that of IL-6 rises." (PMID 35252445, 2022). "So far, these data not only confirm its pivotal role in tumor progression, but also suggest a possible role for anti-IL-1β as a checkpoint inhibitor." (PMID 36712972, 2022). "IL-1β is responsible for the infiltration of myeloid cells, primarily MDSCs, CD11b+Gr-1+ granulocytes, and CD11b+F4/80+Gr-1−/low TAMs in the tumor microenvironment, thereby promoting tumor growth, progression, and poor prognosis." (PMID 36627890, 2022). "The levels of IL-1β in the tumor were highly elevated in the tumor tissues in comparison with adjacent normal tissues (p < 0.0001)." (PMID 35056404, 2022). "In tumor from mice treated with IL-1β + sh-lncRNA CHRF, tumor weight was increased and growth was accelerated by miR-489 inhibitor." (PMID 35711847, 2022). "It has been recently shown that Ca-EVs can activate the inflammasome cascade and IL-1β production in tumor microenvironment-residing cells." (PMID 35530309, 2022). "Previous studies have shown that neutrophils, IL-1β, IL-8, and IL-6 were upregulated and lymphocyte, hemoglobin, and IL-12p70 were downregulated in tumor metastasis, which is consistent with our findings." (PMID 36157224, 2022). "Cryo-thermal therapy alone dramatically upregulated the expression profiles of MDSCs compared to tumor-bearing controls, except for the downregulation of IL-1β and an unchanged level of PD-L1." (PMID 36389684, 2022). "Pyroptosis is a lysis form of programmed death triggered by inflammasome and can rapidly release cellular contents such as pro-inflammatory molecules (IL-1β and IL-18) and antigens into the tumor microenvironment to activate the immune response of the body." (PMID 35847844, 2022). "We found that necrotic tumor cells significantly promoted the expression of the proinflammatory factors TNFα, IFNβ, and IL1β in BMDMs from WT and L/L mice." (PMID 36224346, 2022). "The NLRP3 inflammasome alters the tumor microenvironment via secretion of pro-inflammatory cytokines IL1B (neutral in both cohorts) and IL18 (neutral in mKRAS, conserved in WT, SR = -1.144)." (PMID 36092893, 2022). "The relative abundance of Firmicutes and the F/B ratio showed positive correlations with large tumor numbers, Ki-67-positive cells, colonic mRNA levels of Il1b and Tnfa, and serum levels of IL-1β and IL-6." (PMID 36312913, 2022).